CD4 (CD4 molecule)
Diseases named in the same sentence as CD4 in open-access papers (continued):
Sharing a sentence is not in itself a finding about the gene and the disease.
tuberculosis (continued). "Compared to patients with tuberculosis (TB) alone, those with proven PDH alone showed more profound immunosuppression, with a greater proportion presenting CD4 + counts <50 cells/mm3." (PMID 40961157, 2025). "In addition, the Th1 cell group had higher activity in tuberculosis, antigen presentation pathway, and Th1 and Th2 cell differentiation compared with other cell groups, so the immune response of TPE was mainly mediated by CD4+CD8− Th1 cells." (PMID 40170555, 2025). "However, they cannot compensate for the lack of CD4+ T cells, a subpopulation critical for immune defense in tuberculosis." (PMID 39065554, 2024). "Based on this study, the Official American Thoracic Society/Centers for Disease Control and Prevention/Infectious Diseases Society of America recommended that patients with TBM should not start ART within eight weeks after anti-tuberculosis treatment initiation, regardless of CD4 count." (PMID 38675837, 2024). "The expansion of clonal CD8+ T cells specific of HIV-1 that may invert CD4/CD8 ratio is common in PWH, and it has also been described in response to cytomegalovirus infection, tuberculosis and toxoplasmosis, as well as during the immune response against SARS-CoV-2." (PMID 38812512, 2024). "Similarly, vaccination of elk with BCG, a live attenuated Mycobacterium bovis strain, and the vaccine for human tuberculosis also induces IgG responses but no measurable CD4+ T cell response." (PMID 39132440, 2024). "The BCGosis was confirmed and he underwent anti-tuberculosis treatment with rifampin, isoniazid, and ethambutol, Further laboratory findings demonstrated low lymphocyte count, reduced all lymphocyte subsets including CD3, CD4 and CD8 T cell and CD19 B cell, despite normal NK cells count." (PMID 36810129, 2023). "Therefore, IFN-γ-producing CD4+ T cells are the most involved in the anti-tuberculosis response, and CD8+ T cells are not in close contact with M. tuberculosis-infected cells, which impairs pathogen clearance by these cytotoxic lymphocytes." (PMID 37761328, 2023). "According to our findings, patients with the rs4986790-G (TLR4) allele had higher concentrations of CD4+ lymphocytes compared to patients without the rs4986790-G (TLR4) allele in both the entire sample of HIV patients and in groups with/without tuberculosis coinfection." (PMID 37606452, 2023). "We, therefore, characterised and compared the expression of IL-6, TNF-α, IFN-γ, and IL-10 in whole blood of treatment naïve TB patients stimulated with heat-killed Mycobacterium tuberculosis stratified by HIV status and the level of CD4 count." (PMID 35025927, 2022). "tuberculosis antibody than in those with a negative antibody; however, there were no gender, M. tuberculosis culture, tuberculin test, CT examination, or sputum smear test-specific proportions of CD4+CD25+CD127low Tregs among patients with active pulmonary TB." (PMID 36035072, 2022). "The known importance of CD4 T cells and IFN-γ has led to an enduring tenet of TB immunity: that CD4 T cells secrete IFN-γ to control M. tuberculosis growth in infected macrophages." (PMID 35877763, 2022). "Further studies that delineate the role of GM-CSF in CD4 T cell development and macrophage activation will aid the development of vaccines capable of eliciting M. tuberculosis-specific GM-CSF-producing CD4 T cells and may expediate an end to the global TB pandemic." (PMID 35877763, 2022). "Although CRP values have been found to be elevated in HIV-positive individuals both before and after the initiation of ART without underlying tuberculosis, studies have shown that the CRP value is usually <3 mg/dL, irrespective of their immune status (i.e., CD4 count and viral load)." (PMID 35806852, 2022). "In addition, the differences in some opportunistic infections (tuberculosis, TM, septicemia) and noninfections (non-Hodgkin lymphoma) between the two CD4 count groups were statistically significant." (PMID 35042469, 2022).
tuberculosis (continued). "Thus, during early infection MAIT cells directly contribute to the notoriously slow priming of CD4 T cells, but later during infection MAIT cell stimulation may be an effective host-directed therapy for tuberculosis." (PMID 32811991, 2021). "When CAF01 was applied as an adjuvant for the tuberculosis vaccine known as Hybrid 1 (H1), carrying the hybrid protein of Early Secretory Antigenic Target (ESAT) and Antigen 85B, it induced a strong and long-lasting (3 years) CD4+ T-cell response in a dose-dependent manner." (PMID 33066594, 2020). "Importantly, in the tuberculosis model, CD4+ T-cell but not CD8+ T-cell responses were protective against challenge with M. tuberculosis infection." (PMID 32775465, 2020). "Conversely, the lack of a significant positive correlation between IgG responses and CD4+ T cell counts in this cohort suggests that alterations in M. tuberculosis-specific IgG responses may be related to additional immunosuppressive changes in B cell responses during HIV/TB coinfection." (PMID 32434838, 2020). "Thus, it indicated that B5-NPs may act as a new immunomodulator to promote the proliferation of CD4+ and CD8+ T cells for the control of tuberculosis." (PMID 33271900, 2020). "If we consider patient n°15 as a patient with TB, this brings the specificity of the determination of the percentages of M. tuberculosis specific IFN-γ-containing ascites CD4+ T lymphocytes to 100% for the diagnosis of peritoneal TB." (PMID 30946755, 2019). "Furthermore, information on CD4+ cell counts at follow-up visits, VL at the time of TB diagnosis or second-line ART initiation, M.tuberculosis infection and contact with a known TB case, and smoking were unavailable, limiting the assessment of key risk factors for TB in our study population." (PMID 31664933, 2019). "CD4+ T cell count was normal and tuberculosis antibody was negative." (PMID 30819109, 2019). "In human patients with active tuberculosis, PD-1 was increased on CD4+ T cells but not on CD8+ T cells compared to healthy controls while effective anti-tuberculosis treatment was associated with a down-regulation of PD-1 on CD4+ T cells." (PMID 31484550, 2019). "Studies on protein energy malnutrition (PEM) mice models showed that lymphocytic choriomeningitis virus (LCMV)-specific CD8+ TEM were diminished and TEM were not sustained and in tuberculosis model exhibited reduced lung CD4+ T cell responses to mycobacterial antigens." (PMID 31821327, 2019). "The percentage of CD27− and/or CCR4+ surface homing markers was studied on active TB and LTBI within the IFN-γ+CD4+ T-cells subset after M. tuberculosis specific stimulation." (PMID 30687314, 2018). "Murine TB‐PIGS:ΔXF did, however, result in a greater percentage of triple cytokine‐producing CD4+ and CD8+ cells, which have been suggested to be important in protecting against M. tuberculosis infection." (PMID 29682888, 2018). "This assay is able to discriminate between active TB and LTBI by analyzing CD27 expression on specific M. tuberculosis CD4+ T-cells that respond secreting IFN-γ." (PMID 30687314, 2018). "CPHL is working with the Uganda Virus Research Institute, the National Tuberculosis and Leprosy Control Program, the Infectious Diseases Institute and the National Drug Authority to plan and carry out EQA functions necessary to support quality CD4, EID, and viral load services." (PMID 28879125, 2016). "The M. tuberculosis Ag85A is being tested as TB vaccine candidate, delivered by MVA vector (MVA85A) and has been shown to induce CD4+ and CD8+ T cell responses and when used to boost BCG-vaccinated adult or infant humans." (PMID 26053118, 2015). "Mono- and multifunctional specific CD4+ and CD8+ T-cell responses were evaluated to improve the immune-based detection of active tuberculosis (TB) and latent infection (LTBI)." (PMID 26339657, 2015). "The maternal CD4 count was known in 58%, with 17% on ART, while 16% had been treated for tuberculosis (TB)." (PMID 25495201, 2014).
tuberculosis (continued). "Some studies reported that tuberculosis treatment increased CD4 T cell count among persons with HIV-tuberculosis co infection whereas others indicated anti TB treatment didn’t show any change in absolute CD4 T cell count or restoration of the naive T cell population." (PMID 24592945, 2014). "We investigated 18 HIV-negative patients with MDR-TB for M. tuberculosis (Mtb)- and PPD-specific CD4 T cell responses and followed them over 6 months of drug therapy." (PMID 25048802, 2014). "Recent studies have documented that HIV-positive patients with tuberculosis (TB) who receive antiretroviral therapy (ART) within two weeks of beginning anti-tuberculosis treatment have lower mortality, particularly at low CD4 counts." (PMID 24551061, 2014). "This study describes a scenario in which the potentiation of CD4+ and CD8+ T cell activation and increased production of Th1 cytokines are associated with the clinical cure of tuberculosis in the absence of significant changes in the production of Th2 cytokines." (PMID 23824716, 2013). "Rather, lab efforts have focused on HIV diagnosis, CD4+ T-lymphocyte cell count (CD4), complete blood counts (CBC), biochemistries, HIV viral load, and diagnosis of tuberculosis (TB)." (PMID 24386229, 2013). "tuberculosis coinfection with active tuberculosis responded with a reduction of plasma neopterin to antituberculotic treatment but neopterin levels remained above the baseline levels of HIV negative tuberculosis patients and levels were higher in patients with lower CD4 count." (PMID 26317013, 2013). "This study describes a scenario in which potentiation of CD4+ and CD8+ T cell activation and increased Th1 cytokine production are associated with the clinical cure of tuberculosis in the absence of significant changes in Th2 cytokine production and is accompanied by increased production of IL-10." (PMID 23824716, 2013). "Measurement of the proportion of TNF-α-only secreting M. tuberculosis-responsive CD4+ cells has proved promising to distinguish between active tuberculosis and latent tuberculosis infection but neither earlier data nor our findings have clinically sufficient discriminatory power." (PMID 23966657, 2013). "A previous SR explored the impact of immunosuppression on the proportion of positive results according to a 200 CD4+ T-cell threshold, regardless of whether they had active tuberculosis or not." (PMID 22403663, 2012). "Cell-mediated immunity is essential for control of M. tuberculosis infection; activation of both CD4+ and CD8+ T cells is seen in active TB in humans, as well as in mice after experimental infection." (PMID 22363214, 2012). "However, tuberculosis (TB), caused by Mycobacterium tuberculosis, can occur at any stage of the disease, irrespective of CD4+ T-cell counts, in HIV-1-infected patients and poses a tremendous public health challenge in regions plagued by dual epidemic of HIV and TB." (PMID 22666249, 2012). "Importantly, the CD4 count at which ART was initiated did not significantly alter the magnitude of ART's preventive effect on tuberculosis development." (PMID 22911011, 2012). "Furthermore, a recent study showed that the reduced expression of CD27 on M. tuberculosisantigen-specific CD4+ cells correlated better with persistent active tuberculosis rather than newly diagnosed active tuberculosis." (PMID 22778764, 2012). "The Starting Antiretroviral Therapy at Three Points in Tuberculosis (SAPIT) trial, an open label, randomized controlled trial conducted in a large clinic in Durban, South Africa, enrolled HIV-positive adult patients with a CD4 count <500 and AFB smear-positive TB." (PMID 21234380, 2011). "Thus, neither the frequency of cytokine-positive PPD reactive CD4 T cells nor reactivity towards ESAT-6 or CFP-10 allowed for a distinction between patients with active tuberculosis from successfully treated patients." (PMID 21423578, 2011).
tuberculosis (continued). "In our study, 35.29% of the patients were diagnosed with tuberculosis which was not surprising as TB (median CD4+, 137 cells/mm3) is one of the disease which is increasing in India and our data is in accordance with the other published data from this part of India." (PMID 21396133, 2011). "The objective of the study was to determine IFN-γ responses for the detection of latent tuberculosis infection (LTBI) with QuantiFERON-TB GOLD In Tube (QFT-G-IT) and T-SPOT.TB in HIV patients, and evaluate the influence of CD4 cell count on tests performance." (PMID 21143955, 2010). "This study evaluated the sensitivity of the QuantiFERON TB-Gold In-Tube (QFT-IT) in patients with culture confirmed pulmonary tuberculosis (PTB) in a TB- and HIV-endemic population and the effect of HIV-infection and CD4 cell count on test performance." (PMID 19156218, 2009). "From March to November 2022, consenting HIV positive adults eligible for AHD screening, were offered Visitect CD4 lateral flow assay (LFA), and or subsequently urinary Mycobacterium tuberculosis lipoarabinomannan antigen (TB LAM) and cryptococcal antigen (CrAg) tests." (PMID 41662264, 2026). "Studies have shown that both CD4+ T-cell and CD8+ T-cell lymphocytes are involved in the immune response against tuberculosis, and previous research has reported lower lymphocytes in TB patients." (PMID 40051710, 2025). "In this pilot study, we sought to identify alterations in phenotypic and ex vivo responses of CD4 T cells to Mycobacterium tuberculosis (Mtb) antigens in people with TB with or without T2D." (PMID 40995361, 2025). "Studies using PBMC from people with latent TB without HIV have found CD4+ T cells with common T cell receptor-beta sequences for different M. tuberculosis antigenic epitopes in people who do vs do not progress to active TB." (PMID 39345793, 2024). "At the beginning of the observation period, median CD4 + cell counts were significantly lower among HIV/TB-coinfected individuals compared to the non-tuberculosis group (230 cells/μl vs. 387 cells/μl, respectively, p < 0.001)." (PMID 38492196, 2024). "Debre Markos Referral Hospital laboratory is one of the referral laboratories to which the surrounding health facilities refer diagnostic specimens for laboratory testing, especially for viral load, gene expert for tuberculosis (TB), early infant diagnosis (EID) for HIV test and CD4 test." (PMID 38828425, 2024). "Studies have demonstrated that M. tuberculosis heat shock protein (HSP)-70, 65, and 16 could induce the apoptosis of peripheral blood monocytes and CD4+ and CD8+ lymphocytes in TB patients." (PMID 38004652, 2023). "Our results suggest an alteration in CD4+ immunity in patients with TB-DM that did not normalize after antituberculosis treatment." (PMID 37764989, 2023). "Moreover, uptake of rapid ART increased over time, as did pre‐ART CD4 in this group, whereas pre‐ART CD4 in the intermediate and delayed ART groups changed only slightly, perhaps partly because opportunistic infections as tuberculosis needed to be treated for 2–8 weeks before ART initiation." (PMID 36943729, 2023). "People living with HIV/AIDS who didn’t know other ART users, had tuberculosis and HIV (TB/HIV) co-infection, visited traditional healers, had CD4 count > 351 cells/mm3, and had normal body mass index (BMI) status were more likely to have enrolled into ART lately than their respective counterparts." (PMID 35877661, 2022). "Additionally, using the prime-boost, adjuvant, and viral vectors of M. tuberculosis antigens or BCG, it is possible to generate CD4+ and CD8+ lung Trms that improve protection against TB challenge." (PMID 36009042, 2022). "Because HIV infection is known to decrease M. tuberculosis–specific CD4+ T cell response and aTB induces significant changes in the phenotype of M. tuberculosis–specific CD4+ T cells, patients were grouped according to their HIV and TB status for this analysis." (PMID 33945513, 2021).
tuberculosis (continued). "It is thus an urgent research priority to investigate the profile of the SARS-CoV-2–specific T cells in patients coinfected with HIV-1 and/or active TB and to assess the impact of acute SARS-CoV-2 infection on the M. tuberculosis-specific memory CD4+ T cell response." (PMID 33945513, 2021). "Last, HLA-DR expression on M. tuberculosis–specific CD4+ T cells has been shown to be a robust marker to distinguish active or subclinical TB from latent M. tuberculosis infection, regardless of HIV infection." (PMID 33945513, 2021). "Although anti-tuberculosis immunity is multifactorial involving many types of innate and adaptive immune cells, Th1 immunity mediated by macrophages (MΦs), dendritic cells (DCs) (Antigen Presenting Cells; APCs), CD4, CD8 T cells and non-canonical T cells appears to be the major defense mechanism." (PMID 33365029, 2020). "Indeed, we and others have previously reported that incomplete restoration of Mycobacterium tuberculosis-specific CD4 T-cell responses despite ART contributes to increased incidence of TB." (PMID 32442166, 2020). "In a prospective cohort study of 50 patients with culture-confirmed TB, a significant difference was observed in the M. tuberculosis specific CD8+ T-cell response after anti-TB treatment, but not in the CD4+ T-cell response." (PMID 32544206, 2020). "The most important risk factors for developing active tuberculosis among HIV-positives are low CD4 count, living in high TB-incidence regions and absence of antiretroviral therapy." (PMID 30885144, 2019). "In HIV-TB co-infected patients, where CD4 T cell responses are lacking, a higher dissemination of M. tuberculosis occurs." (PMID 31552007, 2019). "The data suggest that in TB, CXCL10 is secreted by M. tuberculosis-infected macrophages, and undergoes rapid inactivation by membrane bound DPP4 (CD26) expressed on co-localized CD4+ T cells." (PMID 30026741, 2018). "However, we did demonstrate that both the TAM-TB assay and the proportions of CD45RA−CD27− or CD45RA−CD27+ IFN-γ+ CD4+ T cells differed between patients with tuberculosis and those with LTBI." (PMID 28329119, 2017). "Although stimulation with M. tuberculosis lysate led to an increase in GM-CSF production by CD4+ T cells from TB patients, GM-CSF production was not significantly elevated compared to HC subjects." (PMID 29066547, 2017). "In addition, murine airway luminal M.tb antigen-specific CD8+ T effector response induced by intranasal immunization was found long sustained and could confer anti-tuberculosis protection independent of CD4+ T and peripheral T cells." (PMID 29085809, 2017). "Low peripheral CD4+ T-cell count is not the sole cause of higher susceptibility, because HIV–infected persons with a high peripheral CD4+ T-cell count and those prescribed successful antiretroviral therapy (ART) remain more prone to active tuberculosis than HIV–uninfected persons." (PMID 27462092, 2016). "Patients in the rapid-initiation arm of the study (“rapid arm”) received a point-of-care (POC) CD4 count if needed; those who were ART-eligible received a POC tuberculosis (TB) test if symptomatic, POC blood tests, physical exam, education, counseling, and antiretroviral (ARV) dispensing." (PMID 27163694, 2016). "We studied here the expression of Mip-1β and the T cell maturation marker CD27 within CMVpp65-specific CD4+ and CD8+ T cells in relation to age, HIV and active Tuberculosis (TB) co-infection in a cohort of Tanzanian volunteers (≤16 years of age, n = 108 and ≥18 years, n = 79)." (PMID 25974183, 2015). "In TB/HIV co-infected patients however, as infection progresses, there is depletion of neutrophils and monocytes by Mycobacterium tuberculosis and lymphocytes (CD4 especially) by HIV." (PMID 25941570, 2015). "However, patients with tuberculosis co-infection or low CD4+ T cell counts were not included." (PMID 25623944, 2015).